RNU4-79P (RNA, U4 small nuclear 79, pseudogene)
Gene: Small nuclear RNA gene on chromosome 4 (158,395,394 to 158,395,534, forward strand). Ensembl gene ENSG00000199634.
Homologues: Orthologues: chimpanzee U4 (100% identical), macaque U4 (90% identical). Paralogues in human: RNU4-10P (81% identical), RNU4-32P (78% identical), RNU4-28P (73% identical), RNU4-83P (71% identical), RNU4-9P (61% identical), RNU4-13P (60% identical), RNU4-15P (58% identical), RNU4-49P (58% identical), RNU4-67P (58% identical), RNU4-16P (57% identical), RNU4-17P (57% identical), RNU4-44P (57% identical), and 80 more.